RAD51 (RAD51 recombinase)
Diseases named in the same sentence as RAD51 in open-access papers (continued):
Sharing a sentence is not in itself a finding about the gene and the disease.
tumor (continued). "For this aim, one would need sensitive and quantitative detection of the RAD51 protein in tumor cell aspirates or brushings, based for example on immuno-cyto-chemistry or imaging mass spectrometry." (PMID 24618637, 2014). "Next, we investigated the functional contribution of RAD51 to primary tumour growth and metastasis formation in vivo." (PMID 24811120, 2014). "Simultaneously two types of biological alterations were induced in the tumor tissue, especially in the C17 model: a depletion of the DNA-repair protein RAD51 and a stronger in situ detection of the small viral RNA EBER1." (PMID 24618637, 2014). "RAD51 has anti-apoptotic activity in tumor cells, and high expression of this protein is correlated with poor prognosis, resistance to ionizing radiation and drug resistance." (PMID 24708616, 2014). "Taken together, our data demonstrated that B02 significantly enhanced the tumor killing by cisplatin likely through inhibition of RAD51." (PMID 24971740, 2014). "After 14 days RAD51 depletion resulted in regrowth of tumor at the original primary site compared with control mice that displayed disseminated metastatic tumours to the bone and brain." (PMID 24811120, 2014). "Targeting strategies against this gene have been developed as possible anticancer treatments; attempts to inhibit RAD51 have proven to be successful in reducing treatment resistance in tumor cells." (PMID 24708616, 2014). "We show that RAD51 is crucial not only for primary tumor growth but also metastatic spread of 4T1.2 cells." (PMID 24811120, 2014). "The depletion of RAD51 expression in 4T1.2 cells lead to a significant delay in primary tumor growth in vivo (p=0.0013), with sustained depletion of RAD51 at the primary site and overexpression observed in metastatic tumours." (PMID 24811120, 2014). "To identify novel tumor-specific promoters, we examined expression levels of Rad51 paralogs, Rad51B, Rad51C, and Rad51D as well as Rad52 in a panel of normal and tumor cell lines." (PMID 24742710, 2014). "High XRCC3 expression was associated with large tumor size and positive PR and HER2 status, while high RAD51 expression was associated with axillary lymph node metastasis and positive PR and HER2 status." (PMID 23977219, 2013). "This deleterious activity of Rad51p is also intriguing because a number of studies have shown that RAD51 expression is up-regulated in tumor cells." (PMID 23795288, 2013). "Later, amuvatinib inhibition of MET activity was found to lead to reduction of RAD51 expression and to radiosensitization of tumor cells." (PMID 24326130, 2013). "Molecular analysis revealed that treatment with Dox, AN-7, and to a greater degree, AN-7 together with Dox increased tumor levels of γH2AX, the marker for DNA double-strand breaks and decreased the expression of Rad51, a protein needed for DNA repair." (PMID 22384017, 2012). "As cells with increased Rad51 levels are more resistant to DNA damage, there is a selection for tumor cells to have higher Rad51 levels." (PMID 26316936, 2012). "It has been discovered that tumour cells tend to have an elevated level of Rad51 expression, which correlates with their resistance to radiotherapy and chemotherapy (Klein, 2008 ▶)." (PMID 22691778, 2012). "For TAS106-induced down-regulation of BRCA2 and Rad51 to result in tumor radiosensitization, it needs to be maintained during the period of initial DSB repair after X-irradiation." (PMID 21798026, 2011). "RAD51 is a crucial component of the HR pathway and its down-regulation enhances radiosensitivity in tumor cells." (PMID 21798026, 2011). "We therefore conducted experiments to examine the feasibility of using the Rad51 promoter to drive tumor-selective expression of a transgene of interest from an adenovirus vector." (PMID 22174876, 2011). "Upregulation of RAD51 expression is common in tumor cell lines and in a number of human malignancies." (PMID 21858113, 2011).
tumor (continued). "Spearman's analysis also demonstrated that the presence of Rad51-positive baseline foci (P = 0.0078) or EC-induced foci (P = 0.0042) associated with poor EC and DOC tumor response." (PMID 20205718, 2010). "The presence of BRCA1-, γH2AX-, or Rad51-foci before treatment or the presence of Rad51-foci after treatment was inversely correlated with tumor response to chemotherapy." (PMID 20205718, 2010). "We found that foci of BRCA1, γH2AX, and Rad51 prior to treatment and EC-induced foci of Rad51 correlated with tumor response when compared either with the mean tumor volume reduction or the tumor response rate." (PMID 20205718, 2010). "Nevertheless, the different regulatory processes of Rad51 in normal and tumour cells and its role in radiosensitivity offer the possibility for a selective targeting of radiotherapy." (PMID 15785736, 2005). "Overexpression of Rad51 protein in tumour cells renders them resistant against cytotoxic drugs like Cisplatin." (PMID 15956972, 2005). "Even though Rad51 is expressed at higher levels in tumour cells as compared with normal cells, modulation of Rad51 expression has been shown to be more susceptible in tumour cells." (PMID 15785736, 2005). "Instead, the proliferation status of tumour cell lines primarily determines the formation of Rad51 foci after IR." (PMID 15785736, 2005). "In summary, the present study introduces Rad51 expression as independent prognostic factor in NSCLC with elevated levels of Rad51 protein in tumour cells predicting poor outcome of the disease for the individual patient." (PMID 15956972, 2005). "Patients whose tumours displayed high-level Rad51 expression showed a significantly shorter median survival time of 19 vs 68 months (P<0.0001, log-rank test)." (PMID 15956972, 2005). "Rad51, one of the key factors of DNA repair by homologous recombination, has been shown to have antiapoptotic activity in tumour cells." (PMID 15956972, 2005). "In general, the expression level of Rad51 correlates with the fraction of cycling cells and elevated levels of Rad51 protein was found in tumour cells as compared with normal cells." (PMID 15785736, 2005). "LOH was found in the RAD51 region in 32% of tumours, in the RAD52 region in 16%, in RAD54 in 20% and in the BRCA1 and BRCA2 regions in 49% and 44% respectively." (PMID 10507777, 1999). "Multiple small molecules have been reported that inhibit HR by directly blocking RAD51 activity or disrupting its interaction with BRCA2, thereby preventing RAD51 filament assembly and inducing synthetic‐lethal cell death in tumours with heightened dependence on HR." (PMID 41537447, 2026). "Additionally, combining the RAD51 inhibitor B02 with BA-BNCT resulted in tumor cell arrest in the G0/G1 phase, indicating altered cell cycle regulation." (PMID 40824344, 2026). "Consequently, RAD51 is emerging as a promising therapeutic target to restore SL in tumours that have acquired resistance to PARPis." (PMID 41537447, 2026). "RAD51 overexpression has been observed across multiple tumour types." (PMID 41537447, 2026). "Moreover, the result of immunofluorescence staining of γ-H2AX, Ki67 and TUNEL showed that restoring RAD51 expression decreases DNA damage and cell apoptosis, and concurrently increases the tumor growth index." (PMID 39865088, 2025). "Overall, our study identifies TONSL, TIMELESS, RFC3, and RAD51 as tumor dependency genes." (PMID 41179682, 2025). "In addition, the biopsied tumor from patient 29 also exhibited pharmacodynamic responses of nuclear RAD51 (at least 5% of cells with ≥ 5 foci) and pKAP1, which indicated early responses to LMP744-induced DNA damage." (PMID 40439882, 2025). "Inhibition of the KAT2A-SRSF11 axis can promote RAD52 exon 10 skipping, thereby suppressing the interaction of RAD52 with RAD51, impairing HR and promoting radiation-induced tumor cell death across preclinical models, positioning this pathway as a therapeutic vulnerability." (PMID 41198615, 2025).
tumor (continued). "Importantly, assessing RAD51 levels in tumor tissues provides crucial insights into chemotherapy responsiveness and helps predict patient prognosis, thus serving as a potential guide for making informed treatment decisions." (PMID 41199843, 2025). "Furthermore, the elevated expression of RAD51 in Tprolif cells and Treg cells implies a potential regulatory role for RAD51 in the tumour microenvironment (TME) of OSCC." (PMID 41350246, 2025). "Moreover, after DNA damage, cells expressing Klf4 exhibited increased levels of BRCA1 and Rad51, known tumor suppressor genes." (PMID 40699616, 2025). "Similarly, downregulation of POLQ gene expression enhances the activity of RAD51 protein‐mediated DNA repair pathways, thereby increasing tumor cell resistance to platinum‐based agents." (PMID 41473689, 2025). "Notably, HE staining showed that enforced expression of RAD51 in miR-124 overexpressing tumor tissues obviously attenuates TMZ-induced suppression on tumor growth, indicating the potential role of a miR-124-RAD51 axis in TMZ resistance in vivo." (PMID 39865088, 2025). "The present study aims to assess RAD51 protein expression in tumor tissues of patients with advanced HGSOC, analyze its correlation with NACT chemotherapy sensitivity and prognosis, and evaluate the potential of RAD51 as a predictive marker for chemotherapy sensitivity in NACT." (PMID 41199843, 2025). "Notably, TONSL, TIMELESS, RFC3, and RAD51 exhibited significantly higher expression levels within the tumor regions compared to the tumor stromal areas, suggesting their predominant role in tumor cells." (PMID 41179682, 2025). "Also, increased expression of γ-H2AX, p-ATR, RPA32, CHK1, and RAD51 were noted in tumour tissues, as well as a decrease in phosphorylation of the CHK1 signalling molecule (p-chk1)." (PMID 41228271, 2025). "To evaluate pharmacodynamic response, we used immunofluorescence microscopy to measure the levels of TOP1, TOP1cc, RAD51, pNBS1, γH2AX, and pKAP1 in paired pre-treatment and on-treatment tumor biopsies (C1D2, 2–4 h after dosing) from 6 patients receiving LMP744 at the MTD." (PMID 40439882, 2025). "This reinforces RAD51's role in driving aggressive tumour behaviour in OSCC." (PMID 41350246, 2025). "Also in vivo, BBIT20 inhibited HR DNA repair as evidenced by the significant decrease of BRCA1 and RAD51 expression levels in tumour tissues." (PMID 40275348, 2025). "Overall, the tumor displayed a profile of unusual high genomic instability which suggests a possible origin from germline predisposing mutations in the DNA repair genes BRCA1 and RAD51." (PMID 38512353, 2024). "This was further confirmed by the quantification of the number of RAD51 foci‐positive cells and in vivo RAD51 expression in tumor tissues, indicating that BMN treatment induced HR response and DNA repair, which could be reduced by PAZA treatment." (PMID 38482976, 2024). "We also show that SCAF1 deficiency partly rescues RAD51 loading in cells lacking the BRCA1 tumor suppressor." (PMID 38880245, 2024). "One of the RAD51 high ER-negative breast cancer cases was an ERBB2-positive tumor." (PMID 38648056, 2024). "Additionally, it significantly inhibits the expression of NF-κB signaling-dependent proinflammatory genes IL-6 and IL-1B through RAD51, thus blocking the STING-associated anti-tumor immunity in stromal tumor-infiltrating lymphocytes (sTIL)." (PMID 39638799, 2024). "In addition, increased levels of the DDR factor RAD51 and decreased levels of γH2AX were observed in tumor sections from the TMZ treatment group." (PMID 38600891, 2024). "As a result, H2AX loss restores replication fork stability and increases chemoresistance in BRCA1/2-deficient tumour cells without restoring homology-directed DNA repair, as highlighted by the lack of DNA damage-induced RAD51 foci." (PMID 38789420, 2024).
tumor (continued). "In addition, it significantly inhibits the expression of NF-κB signaling dependent proinflammatory genes IL-6 and IL-1B through RAD51, thus blocking the STING-associated anti-tumor immunity in stromal tumor-infiltrating lymphocytes (sTILs)." (PMID 39638799, 2024). "Also, the displayed sensitization of malignant cells to radiation was attributed to the decreased formation of RAD51 foci as well as diminished phosphorylation of DNA-PKcs in irradiated tumor cells." (PMID 39564119, 2024). "Consequently, the number of RAD51 and RAD54 foci increased upon BLM_CPP exposure, indicating enhanced DNA repair, which is known to be associated with cell cycle progression and tumor growth." (PMID 38421735, 2024). "Interestingly, the BARD1 protein interacts with BRCA1 (BRCA1-BARD1) forming a tumor suppressor complex, which is an E3 ubiquitin ligase necessary for DNA double-strand breaks repair by RAD51-mediated homologous recombination." (PMID 38978731, 2024). "Gemcitabine is a Rad-51 inhibitor that may help in increasing drug concentration at tumor sites and limit gastrointestinal complications." (PMID 38899244, 2024). "Unlike the RECAP test, the RAD51-FFPE test utilizes FFPE diagnostic tumor samples, eliminating the need for fresh tumor tissue." (PMID 37725154, 2023). "The top-scoring genes altered in the four gene sets included many genes associated with cell apoptosis and DNA damage, such as GADD45A, DDIT3, BAX, CASP1, CASP8, ATM, and FANCD2, demonstrating that diminishment of RAD51 contributes to the tumor suppressive effect." (PMID 37175611, 2023). "The expression of RAD51 was immunohistochemically examined in different parts of the tumor." (PMID 36837562, 2023). "Both studies showed that inhibition of RAD51 markedly suppressed tumor growth in mouse xenografts." (PMID 37798649, 2023). "In addition, a decreased synthesis of nuclear RAD51 have also been shown in PTEN-mutant tumor cells." (PMID 37509303, 2023). "Furthermore, these cells were unable to recruit RAD51 to sites of DNA damage after cisplatin treatment, which is in line with the data obtained from HBCx-14 tumours." (PMID 37029129, 2023). "Twenty-five TNBC PDX of the previous cohort with additional 7 PDX models, established at the Netherlands Cancer Institute (NKI), were further analysed on a genomic level with their matched patients’ tumours and functionally tested for homologous recombination repair based on RAD51 foci formation." (PMID 37029129, 2023). "Therefore, to further characterise these models at the baseline, we used RAD51 foci in tumour cells at the S-G2 phase of the cell cycle (geminin positive cells) by immunofluorescence (IF) to assess the HRR functionality." (PMID 37627223, 2023). "All PDAC cells used in this study and KP‐4 tumor tissues showed RAD51 expression." (PMID 36262061, 2023). "The underlying mechanism might be that cediranib could increase tumor hypoxia and inhibit platelet-derived growth factor receptor to downregulate BRCA1/2 and RAD51, thus decreasing a homology-deficient DNA repair to confer olaparib sensitivity." (PMID 35466318, 2022). "Rad51 inhibitors may sensitize tumor cells to chemotherapeutic agents, render tumors to be more efficient in HRR, and to be more responsive to PARP inhibitors targeting HRR-deficient tumors with mutated BRCA1/2 genes." (PMID 35875146, 2022). "In multiple tumor types, Rad51 is critical for tumor metabolism, metastasis and drug resistance." (PMID 35875146, 2022). "With more and more evidence showing that Rad51 may participates in the metabolic adaptation of tumorigenesis, the role of Rad51 in tumor metabolism and its mechanisms require more studies." (PMID 35875146, 2022). "Tumor samples from ovarian patients were stained and scored for RAD51." (PMID 36091750, 2022). "Dysregulated expression of Rad51 has been commonly discovered in various tumor types." (PMID 35875146, 2022).
tumor (continued). "Additionally, we primarily discussed the role of rad51 in tumor metabolism, metastasis, resistance to chemotherapy and poly-ADP ribose polymerase (PARP) inhibition." (PMID 35875146, 2022). "Both transcriptional and post-translational modifications of Rad51 are essential for the expression level and function of Rad51, which may open new avenues for anti-tumor strategies." (PMID 35875146, 2022). "Besides, Rad51 also participates in the tumor metabolism, metastasis and chemotherapeutic resistance." (PMID 35875146, 2022). "Thus, therapies based on the Rad51 promoter will be highly tumor-specific and open new avenues for targeting a variety of tumor types." (PMID 35875146, 2022). "In addition, we identify the RAD51 inhibitor as a potential synthetic lethal partner for other DDR inhibitors extending the applicability of our identified compound to other tumor types." (PMID 35646698, 2022). "Moreover, inhibition of HR, through chemical as well as transgenic inhibition of recombinase RAD51, reduces genomic instability as well as tumor growth in a subcutaneous model of EAC." (PMID 36428789, 2022). "RAD51 expression is an independent predictor for tumor progression as well as tumor recurrence." (PMID 35996502, 2022). "RAD51 inhibition may lead to increased tumor radiosensitivity, and it has been reported as a potential target of berberine in osteosarcoma radiosensitization." (PMID 35875060, 2022). "Additionally, we primarily discussed the role of Rad51 in tumor metabolism, metastasis, resistance to chemotherapeutic agents and poly-ADP ribose polymerase inhibitors." (PMID 35875146, 2022). "However, we found that the percent of (tumor and stromal) RAD51+ cells trended higher in tumors expressing BRCA2-001/Short compared to those expressing BRCA2-201/Long." (PMID 36344544, 2022). "In addition, miR-96 and directly targets the coding region of Rad51, and overexpression of miR-96 in tumor cells reduces the levels of Rad51 and sensitizes tumor cells to DNA damage agents." (PMID 35875146, 2022). "Interestingly, overexpression of RAD51 modified expression of immune‐regulatory pathways in vitro, while RAD51‐High tumours showed exclusion of cytotoxic T cells in situ." (PMID 33709473, 2021). "RAD51 nuclear foci in untreated tumor samples were studied in two small studies." (PMID 33670893, 2021). "Therefore, measurement of RAD51 subnuclear foci is a functional assay for detecting HRD in tumor samples." (PMID 34722237, 2021). "Additionally, assays aimed at determining the capacity of tumor cells to form RAD51 foci when challenged with a DNA-damaging treatment have been proposed as biomarkers of response to PARP-i (NCT04780945)." (PMID 34208195, 2021). "RAD51 depletion leads to tumor cell sensitization to chemotherapy and can slow tumor growth." (PMID 34208492, 2021). "MDC1 is a tumor suppressor that interacts with Rad51 to facilitate HR repair." (PMID 34880209, 2021). "At present, studies on the RAD51 gene mainly focus on the interaction between tumor suppressors, the cell cycle, and apoptotic regulators to promote the transformation of normal breast epithelial cells into tumor molecules." (PMID 34484285, 2021). "According to our findings, since CD81 promotes Rad51-dependent DNA repair and thus acts as an intrinsic factor of tumor radioresistance, we speculate that combination of radiotherapy and CD81 inhibitor may promote therapeutic effect by attenuating HRR in GBM." (PMID 33919192, 2021). "RAD51 overexpression leads to excessive and improper recombination, thereby triggering genomic instability, which successively drives malignant transformation, contributes to tumor progression, and even induces anticancer drug tolerance." (PMID 33952262, 2021). "However, there have been reports of the restoration of RAD51 foci in breast cancer tumours collected on PARPi progression (in 4/4 patients on PARPi progression, 6/7 patients on PARPi or platinum progression)." (PMID 35008208, 2021).